LNCNEF (lncRNA neighboring enhancer of FOXA2)
Synonyms: lncRNA-NEF; formerly LINC01384
Gene: Long non-coding RNA gene on chromosome 20 (22,587,517 to 22,607,856, reverse strand). Ensembl gene ENSG00000237396.
Diseases named in the same sentence as LNCNEF in open-access papers:
LNCNEF is named in the same sentence as 1 disease in open-access papers, as found by Europe PMC text mining. Sharing a sentence is not in itself a finding about the gene and the disease. The quoted sentences say what the papers report.
benign (1 paper, 2022). "The expression levels of MPPED2-AS1, LNCNEF, and LOC100129129 were significantly reduced in the malignant nodules compared to those in the benign nodules and paired normal thyroid tissues." (PMID 36132147, 2022).